SLC30A3 (solute carrier family 30 member 3)
Description:
Probable proton-coupled zinc ion antiporter mediating the import of zinc from cytoplasm into synaptic vesicles and participating to cellular zinc ion homeostasis in the brain.
Synonyms: ZNT3
Tractability: Small molecule: a structure with a bound ligand is known. Antibody: UniProt predicts a signal peptide or a membrane-spanning region; its Gene Ontology location is reachable by antibodies, with medium confidence.
Gene: Protein-coding gene on chromosome 2 (27,253,515 to 27,275,817, reverse strand). Ensembl gene ENSG00000115194.
Subcellular location: Cytoplasmic vesicle, secretory vesicle, synaptic vesicle membrane; Synapse, synaptosome; Late endosome membrane; Lysosome membrane
Subcellular location (Human Protein Atlas): Vesicles; Cytosol; Nucleoli; Nucleoplasm
Pathways (Reactome):
Transport of small molecules: Zinc efflux and compartmentalization by the SLC30 family
Gene Ontology:
Molecular function: protein binding; zinc ion transmembrane transporter activity; AP-3 adaptor complex binding; monoatomic cation transmembrane transporter activity
Biological process: zinc ion import into lysosome; zinc ion transmembrane transport; response to zinc ion; monoatomic cation transport; transmembrane transport; zinc ion import into organelle; zinc ion import into synaptic vesicle
Cellular component: cytoplasm; cytoplasmic vesicle membrane; late endosome; late endosome membrane; lysosomal membrane; microvesicle; synaptic vesicle; transmembrane transporter complex; neuron projection; plasma membrane; clathrin-sculpted vesicle; cytoplasmic vesicle; glutamatergic synapse; hippocampal mossy fiber; hippocampal mossy fiber to CA3 synapse; membrane; synapse; synaptic vesicle membrane; vesicle membrane
Genetic constraint (gnomAD): Loss-of-function variants: 20 observed, 35.31 expected, observed/expected ratio (o/e) 0.57, 90% interval 0.4 to 0.82. The upper end of that interval is the gene's LOEUF score, 0.82, which puts it in group 3 of 6, group 1 being the genes least tolerant of losing a copy. Missense variants: 401 observed, 523.62 expected, observed/expected ratio (o/e) 0.77, 90% interval 0.7 to 0.83. Synonymous variants: 217 observed, 224.21 expected, observed/expected ratio (o/e) 0.97, 90% interval 0.87 to 1.08.
Homologues: Orthologues: chimpanzee SLC30A3 (100% identical), macaque SLC30A3 (99% identical), guinea pig SLC30A3 (94% identical), dog SLC30A3 (93% identical), mouse Slc30a3 (89% identical), rat Slc30a3 (81% identical), rabbit SLC30A3 (59% identical), pig SLC30A3 (58% identical), Drosophila melanogaster ZnT33D (38% identical), Drosophila melanogaster ZnT35C (38% identical), Drosophila melanogaster ZnT63C (22% identical), Caenorhabditis elegans cdf-1 (22% identical), and 1 more. Paralogues in human: SLC30A2 (48% identical), SLC30A8 (40% identical), SLC30A4 (34% identical), SLC30A1 (23% identical), SLC30A10 (20% identical), SLC30A6 (19% identical), SLC30A7 (17% identical), SLC30A5 (17% identical).
Diseases named in the same sentence as SLC30A3 in open-access papers:
SLC30A3 is named in the same sentence as 50 diseases in open-access papers, as found by Europe PMC text mining. Sharing a sentence is not in itself a finding about the gene and the disease. The quoted sentences say what the papers report.
Alzheimer disease (12 papers, 2009 to 2025). A progressive, neurodegenerative disease characterized by loss of function and death of nerve cells in several areas of the brain leading to loss of cognitive function such as memory and language. "The ZnT3 protein, encoded by the SLC30A3 gene, is located mainly in the brain, and to date, the SLC30A3 polymorphism has not been linked to human metabolic diseases but has been linked to schizophrenia and Alzheimer’s disease." (PMID 39850557, 2024). "To confirm that SLC30A3 expression is indeed dysregulated in Alzheimer’s disease, we established an AD cell model by treating SH-SY5Y cells with OKA." (PMID 41300833, 2025). "Consequently, dysregulation of SLC30A3 could contribute to the onset and progression of Alzheimer’s disease by altering zinc-mediated immune functions." (PMID 41300833, 2025).
depression (7 papers, 2016 to 2025). "In contrast, a polymorphism of the SLC30A3 gene (rs11126936) has been shown to be associated with major depressive disorder in a cohort of Asian participants, with those homozygous for the minor allele having reduced risk of MDD." (PMID 36203844, 2022).
schizophrenia (7 papers, 2016 to 2024). A major psychotic disorder characterized by abnormalities in the perception or expression of reality. "Emerging data suggest that polymorphisms of SLC30A3, the gene encoding ZnT3, is also linked to a higher risk of schizophrenia." (PMID 37432243, 2023). "Subsequent work on variants in the SLC30A3 gene using a UK case-control cohort revealed that the minor alleles of four SNPs, including rs11126936 and rs11126929, were associated with schizophrenia in female patients." (PMID 36203844, 2022). "SLC30A3 polymorphisms in humans can lead to ZnT-3 loss of function phenotypes, that were reported to increase seizure susceptibility as well as the risk of schizophrenia." (PMID 30233309, 2018). "In this pilot study, we tested the hypothesis that the presence of a minor allele of two variants in the gene encoding ZnT3 (SLC30A3) affects brain glutamate and cognitive activity in patients with schizophrenia and bipolar affective disorder." (PMID 36203844, 2022). "Fifteen patients with schizophrenia (SCZ), 15 with bipolar affective disorder type 2 (BD), and 14 healthy volunteers (HV) were genotyped for two SLC30A3 single nucleotide polymorphisms (rs11126936 and rs11126929)." (PMID 36203844, 2022). "A post-mortem study of gene expression in two separate cohorts of patients with schizophrenia revealed reduced transcripts from the SLC30A3 gene, in the prefrontal cortex: Brodmann area (BA) 10 (Charing Cross Hospital Prospective Collection) and BA 9 (Harvard Brain Bank)." (PMID 36203844, 2022). "SLC30A3 genotype for rs11126929 A/G and rs11126936 SNPs by group (HV, healthy volunteers; SCZ, patients with schizophrenia; BD, patients with bipolar affective disorder type 2)." (PMID 36203844, 2022).
colorectal cancer (2 papers, 2024). A primary or metastatic malignant neoplasm that affects the colon or rectum. "The mechanism of SLC30A3 suppression in colorectal cancer is currently poorly understood." (PMID 39596116, 2024). "Importantly, the expression profile of SLC30A3 in colorectal cancer (downregulated in 92% of samples) correlates with SLC30A10." (PMID 39596116, 2024). "Within the top five genes based on WRF (Ensemble 1 and Ensemble 2), SLC30A3, MOS, C1ORF61, and MBL1P genes were found to have an association with CRC, gene PAGE2, a gene from cancer-germline genes, was found to be upregulated in Caco-2 colorectal cancer cell line." (PMID 39897528, 2024).
glioblastoma (2 papers, 2024 to 2025). The most malignant astrocytic tumor (WHO grade IV). "In addition to the expression changes of SLC30A3 by metal ion stimulation, HDAC1 overexpressed in glioblastoma inhibits the expression of SLC30A3 by deacetylation modification, which is related to the malignant phenotype of glioblastoma." (PMID 38533032, 2024). "SLC30A3 is a highly expressed tumor suppressor in glioblastoma (GBM)." (PMID 41583444, 2025).
cervical cancer (1 paper, 2022). A primary or metastatic malignant neoplasm involving the cervix. "For tumor stages, SLC30A1, SLC30A7 and SLC30A10 groups significantly varied, whereas SLC30A2, SLC30A3, SLC30A4, SLC30A5, SLC30A6, SLC30A8 and SLC30A9 did not significantly differ in cervical carcinoma." (PMID 35154468, 2022). "However, the expression of SLC30A3, SLC30A4, SLC30A5, SLC30A6 and SLC30A9 genes in cervical cancer was not statistically significant compared to the corresponding paracancerous tissues." (PMID 35154468, 2022).
glaucoma (1 paper, 2018). Increased pressure in the eyeball due to obstruction of the outflow of aqueous humor. "Thus, it is tempting to hypothesize that POU6F2 exerts its effects on retinal ganglion cell survival in an injury and chronic neurodegeneration (glaucoma) context by modulation of Slc30a3." (PMID 29370175, 2018).
neuroblastoma (1 paper, 2010). Neuroblastoma (NB) is the most common solid, extracranial childhood tumor. "MYCNOS and SLC30A3 were confirmed to be correlated with the status of expression of MYCN in neuroblastoma." (PMID 20380745, 2010). "The five genes identified as candidate genes involved in neuroblastoma progression were: MYCN (neuroblastoma derived), NPW (neuropeptide W), SLC30A3 (solute carrier family 30, member 3), MYCNOS (neuroblastome derived opposite strand), and MYCN* (v-myc myelocytomatosis viral related oncogene)." (PMID 20380745, 2010).
prostate carcinoma (1 paper, 2020). A carcinoma that arises from epithelial cells of the prostate gland. "PSMA1, MRAS, LEP, SLC30A3, and RNF7 were found closely related with prostate cancer." (PMID 32528533, 2020).
protein misfolding diseases (1 paper, 2025). "The association of reduced SLC30A3 expression with multiple neurodegenerative diseases in the GSEA results reinforces the importance of zinc in protein misfolding diseases." (PMID 41300833, 2025).
tumor (6 papers, 2018 to 2025). "SLC30A3, a factor regulated by a super-enhancer (SE), functions as a tumor suppressor and exhibits significantly lower expression in GBM." (PMID 40565099, 2025). "Aberrant expression of SLC30A3 may disrupt intracellular zinc homeostasis, exacerbate oxidative stress, and contribute to epithelial damage and tumor immune evasion in endometrial tissue." (PMID 40777132, 2025). "For person neoplasm cancer status, LOC285000 and LEP could distinguish the prognosis of patients free from neoplasm, while SLC30A3 and DYNC1I1 were significant for patients with neoplasm." (PMID 32528533, 2020).
cancer (4 papers, 2019 to 2024). A tumor composed of atypical neoplastic, often pleomorphic cells that invade other tissues. "Taken together, these findings may suggest that the expression and methylation levels of the genes SLC30A10 and SLC30A3 may have predictive value for the sensitivity of cancer cells to platinum drugs, also inthe case of KRAS-mutated CRC cells." (PMID 39596116, 2024). "In contrast, overexpression of SLC30A3 in HuTu80 resulted in an ~3.3 times lower IC50 of cisplatin, which suggests greater cancer cell sensitivity to chemotherapy associated with this gene expression." (PMID 39596116, 2024). "Furthermore, by screening through the criteria of the PPI network, cancer-related pathway and TRS modeling, essential features with gene symbols of EPB41, PSMA1, FGFR3, MRAS, LEP, C7orf46, LOC285000, LBP, ZNF35, SLC30A3, LECT2, RNF7, and DYNC1I1 were identified as PRBs for COAD patients." (PMID 32528533, 2020).
mental illness (1 paper, 2022). "This study supports the further investigation of SLC30A3 and its role in glutamatergic neurotransmission and in the neuropathology of mental illness." (PMID 36203844, 2022).
SLC30A3 also shares sentences with these, for which no sentence is quoted: Cognitive impairment (7 papers); Zinc deficiency (5); epilepsy (4); Huntington disease (4); Parkinson disease (4); amyotrophic lateral sclerosis (3); dementia (3); neurodegenerative disease (3); cerebral amyloid angiopathy (2); cognitive decline (2); experimental autoimmune encephalomyelitis (2); Hyperglycemia (2); ischemia (2); Obesity (2); Stroke (2); alcohol dependence (1); amyloid (1); Anxiety (1); autism (1); bipolar affective disorder (1); brain disorder (1); cerebral infarction (1); Cerebral ischemia (1); colitis (1); dementia with Lewy bodies (1); glioma (1); infarction (1); influenza (1); metabolic disease (1); microcephaly (1).
A further 7 diseases each share a sentence with SLC30A3 in 1 paper.